NRP1 (neuropilin 1)
Diseases named in the same sentence as NRP1 in open-access papers (continued):
Sharing a sentence is not in itself a finding about the gene and the disease.
infection (continued). "Neuropilin-1 (NRP1) is expressed in abundance in the olfactory epithelium, binds to furin-cleaved substrates, and enhances infection by SARS-CoV-2." (PMID 34445619, 2021). "NRP1 is abundant in the central nervous system especially in olfactory bulb, which potentiates the infection of CNS through entry of the olfactory epithelial cells in nasal cavity." (PMID 34168096, 2021). "Neuropilin 1 (NRP1) is a cellular protease of which the overexpression significantly increases the infection of epithelial cells by EBV; when inhibited, on the other hand, it reduces infection by 50%." (PMID 34239514, 2021). "The loss of its furin cleavage site resulted in the impairment of NRP-1-potentiating ACE-2 infection of host cells." (PMID 35071285, 2021). "The group also observed an increase in apoptotic beta cells in the islets upon infection; all of which were reversed using a NRP1 antagonist indicating that NRP1 is an entry factor that the virus utilizes to invade beta cells." (PMID 34561952, 2021). "Using a conditional knockout model, we deleted Nrp1 either before infection or after CD8 T cell memory had been established." (PMID 31118303, 2019). "This lead to the T cell response to FS73 being dominated by Nrp1 high expressing (Nrp1hi) cells during the acute infection, whereas there were more similar proportions of Nrp1hi and Nrp1lo cells at most times during the response to FS73R." (PMID 31118303, 2019). "As in previous experiments, tamoxifen was administered before infection to delete Nrp1, and then splenic CD8 T cells were purified on d28 postinfection and adoptively transferred into congenic recipient mice." (PMID 31118303, 2019). "We confirmed its knockdown efficiency both in vitro and in vivo by transfection and infection of Nrp1 shRNA, respectively." (PMID 30683854, 2019). "We found that, after 48 h infection, there was a downregulation of β-catenin in NRP1-depleted cells compared with controls." (PMID 31167777, 2019). "At least in part, this accumulation was due to migration of nTreg cells to the site of infection, as evidenced by enhanced expression of Neuropilin-1, CD39, CD73, Helios and CCR5." (PMID 26512987, 2015). "By introducing this protein into resistant cells, we demonstrated that susceptibility to infection can be reinstated, indicating that the absence of NRP1 plays a key protective role at the materno-fetal barrier." (PMID 41288331, 2025). "Inhibition of NRP-1 in cultured LS-DRG neurons from hACE2 mice reduced infection to a greater extent than in WT neurons, indicating that NRP-1 can serve as an entry factor to enhance infection in the presence of hACE2 expression or an alternative entry factor independent of hACE2." (PMID 39125815, 2024). "ACE2 and NRP1 serve as established receptors that facilitate the entry and infection of SARS-CoV-2." (PMID 38392839, 2024). "The electrostatic potential energy map predicted the susceptibility of bovines to cross-species infection by SARS-CoV-2 and also whether ACE2, AXL, and NRP1 proteins might serve as potential receptors for SARS-CoV-2." (PMID 38012648, 2023). "Therefore, we sorted Nrp-1+ and Nrp-1- CD8+ T cells from spleens of PbA-infected C57BL/6 mice 6 days after infection and analyzed the gene expression profile by Clariom S microarray analysis." (PMID 38019895, 2023). "Since we did not detect any differences in the activation state of CD8+ T cells from Nrp-1KO mice and Nrp-1WT mice in the spleen or blood after PbA infection or upon stimulation in vitro, Nrp-1 seems to be a marker for activated CD8+ T cells, but dispensable for efficient initial T cell priming." (PMID 38019895, 2023). "Based on their localization, it is likely that integrins function as the EBV receptor for infection at the basal layer, whereas it is likely EphA2 and NRP1 function as EBV receptors for infection at the apical surface and within the suprabasal layers where productive replication occurs." (PMID 36630458, 2023).
infection (continued). "Therefore, we analyzed Nrp-1 expression on CD8+ T cells during an acute LCMV-WE infection, in which the cytotoxic function of CD8+ T cells is crucial for virus clearance but also responsible for emerging immunopathology." (PMID 38019895, 2023). "Besides ACE2, the most prominent receptor, other receptors that mediate CoV2 infection of human cells include neuropilin-1 (NRP1), Eph receptors, transmembrane serine protease 2 (TMPRSS2), P2X7, and CD147 (BSG)." (PMID 38203569, 2023). "A fascinating and impactful emerging theme is that the NRP1 pathway may influence infection by a wide range of viruses through the recognition of CendR motifs on viral glycoproteins." (PMID 35696571, 2022). "Here, we identify Neuropilin-1, a host factor for infection by severe acute respiratory syndrome coronavirus 2 (SARS-CoV-2), Epstein-Barr virus (EBV), and human T cell lymphotropic virus type 1 (HTLV-1), as a direct cargo sorted by the endosomal SNX-BAR sorting complex promoting exit 1 (ESCPE-1)." (PMID 35696571, 2022). "Because HTLV-1 mimics VEGF to recruit heparan sulfate proteoglycans and neuropilin-1, which are involved in cellular infection, VEGF could become a selective competitor of HTLV-1 when HTLV-1 enters into non-infected cells." (PMID 36290496, 2022). "Interestingly, we observed the same tendency of NRP1 protein for decreased expression with infection in the three cell types, when the MOI was high." (PMID 35335638, 2022). "Of note, although ACE2 expression is low in pulmonary epithelial cells and ECs, NRP1 is abundantly expressed in these cells, indicating NRP1 may be a necessary host factor for efficient infection and spreading." (PMID 34307198, 2021). "S1D), showing that NRP1 can potentiate infection in the presence of other host factors." (PMID 33082293, 2020). "Blocking interactions with HS chains and NRP-1 also decreased infection of CD4+ T cells by HTLV-1." (PMID 21994754, 2011). "Our results suggest that such a treatment should be envisioned with caution in the context of BBB, as it could increase the availability of the Neuropilin-1 to the virus and thereby, could facilitate infection of the BBB by HTLV-1." (PMID 19008946, 2008). "Hence, NRP1 has merely been called a host factor required for infection of particular cells." (PMID 41288331, 2025). "Perhaps, Nrp1 might impact infection in cases where it is more highly expressed." (PMID 37375521, 2023). "However, the precise relationship between bovine ACE2, AXL, NRP1, and the S protein in terms of predicting infection capability remains unclear." (PMID 38012648, 2023). "Interestingly, olfactory tubercles, paraolfactory gyrus, and olfactory epithelium express elevated levels of neuropilin-1, so their direct infection by SARS-CoV-2 may explain some of the neurological manifestations." (PMID 37175995, 2023). "This is in line with recent reports, suggesting that ACE2 and TMPRSS2 expression might be prerequisite for BSG and NRP1 to exert their infection-potentiating activity Interestingly, previous studies have shown that ACE2 expression is regulated by IFNα and IFNγ signalling." (PMID 35837388, 2022). "Besides the ACE2 receptor, S protein may exploit additional receptors for infection, such as TLRs, CLRs, NRP1, and GRP78, which recognize the carbohydrate moieties clustered on S protein." (PMID 34278967, 2021). "The infection process of EBV relies on interactions between the virus and specific receptors on the surface of host cells, including CD21, NRP1, EphA2, and, more recently, discovered receptors such as R9AP and DSC2." (PMID 42112902, 2026). "NRP-1 appears to potentiate the virus’ interaction with the ACE2 receptor, acting in synergy, and therefore increases the infection rate when compared to each receptor independently." (PMID 40584180, 2025).
infection (continued). "Therefore, based on the in-silico protein-protein interaction prediction result and expression analysis study from enteric and respiratory cell lines infection, NRP-1 might play the role of co-receptor for BCoV entry and pathogenicity of the virus into the bovine host cell." (PMID 39941096, 2025). "Such infection potentially occurs by exploiting the interaction with ACE2, CD147, and NRP1 proteins." (PMID 39950320, 2025). "The ACE2 enzyme is stimulated by the transepithelial serine protease type II TMPRSS2 or cathepsin L. Additional receptors involved in the infection process have also been described thus far: CD147/EMMPRIN/Basigin, Axl and Neuropilin-1 (NRP1)." (PMID 38592169, 2024). "Control, ACE2-silenced and NRP1-silenced cells were then infected with SARS-CoV-2, lineage B.1, and the viral load was assessed by real-time PCR 6 h post-infection (p.i.)." (PMID 38849411, 2024). "Primary OM cells in ALI expressed angiotensin-converting enzyme 2 (ACE-2), neuropilin-1 (NRP-1), and several other known SARS-CoV-2 receptor and were highly vulnerable to infection." (PMID 38098019, 2023). "Both teams also showed that NRP1 potentiates and enhances SARS-CoV-2 entry and infection, in the presence of ACE2 and TMPRSS2, consistent with the role of NRP1 as co-receptor." (PMID 37047226, 2023). "Novel host cell factors required for infection were found to be Vascular endothelial growth factor (VEGF) and semaphorin-binding receptor Neuropilin-1 (Nrp-1)." (PMID 37794981, 2023). "Tyrosine-protein kinase receptor UFO (AXL) and neuropilin-1 (NRP1), a newly discovered viral receptor of SARS-CoV-2, promote the entry of SARS-CoV-2 into host cells and infection." (PMID 37644471, 2023). "We used the rescued strain rSczy3 to infect CEKs and performed qRT-PCR to evaluate the relative expression levels of CTSL, CTSB, Abl1, Abl2, IFITM3, ADAM17, TMPRSS2, NRP1, and CD74 at 12 and 24 h post-infection." (PMID 37376546, 2023). "The dopamine receptor D2 antagonist alimemazine, one of the phenothiazines, was previously shown to effectively inhibit the infection of SARS-CoV-2 by interfering with the interaction between the SARS-CoV-2 S protein and neuropilin-1." (PMID 37632009, 2023). "The cleaved S1 subunit C-terminus also facilitates the binding of attachment receptors, such as neuropilin-1 (NRP1), to further promote the infection of lung epithelial cells in human and other animal models." (PMID 37948454, 2023). "Tyrosine-protein kinase receptor UFO (AXL), Neuropilin-1 (NRP1), and CD209 act as SARS-CoV-2 receptors which play critical roles in SARS-CoV-2 invasion and infection." (PMID 36008961, 2022). "To determine the role NRP1 plays in the infection process of SARS-CoV-2, we searched the biological pathways involving NRP1 in the WikiPathways database." (PMID 36338984, 2022). "Apart from NRP1, its homologous form NRP2 was found to contribute to the infection by certain viruses as well, namely, Lujo virus (LUJV) and human cytomegalovirus (HCMV) which use NRP2 as their viral entry point." (PMID 35955539, 2022). "Neuropilin-1 (NRP1), a transmembrane receptor that is conservative compared to SARS-CoV-2, has been identified as a host mediator for SARS-CoV-2 cell entry and infection." (PMID 36408220, 2022). "Using siRNAs to knock down the expression of these individual receptors, we find that NRP1 and TPCN2 are required for SARS-CoV-2 entry into and productive infection of astrocytes." (PMID 36314791, 2022). "SU mediates infection by binding to cellular entry factors heparin sulfate proteoglycans (HSPG), glucose transporter 1 (GLUT-1), and neuropilin-1 (NRP-1)." (PMID 36159878, 2022). "Oral cavity expresses critical protein receptors such as ACE-2 and NRP-1 and enzymes such as TMPRSS2 required for viral entry and infection." (PMID 34749700, 2021). "Eventually, NRP1-mediated endocytosis of the CendR peptide of SARS-CoV-2 promotes virus entry, resulting in infection." (PMID 34206057, 2021).
infection (continued). "For example, Neuropilin-1 (NRP-1) binds S1 following furin cleavage, which promotes viral entry and infection." (PMID 33800954, 2021). "WB analysis revealed that NRP‐1 protein expression dramatically decreased in GBC‐SD and NOZ cells after infection." (PMID 32951327, 2020). "While Nrp1 was induced with these kinetics in both FS73 and FS73R infections, the induction was significantly greater from days 14 to 21 after FS73 infection but not significantly different thereafter." (PMID 31118303, 2019). "It is particularly interesting that Nrp1 deletion only affects recall responses in FS73R-infected mice, despite observing lower Nrp1 expression after infection with this persistent strain." (PMID 31118303, 2019). "By 7 days post infection, CD11c+ cells in the brain express high levels of both VEGFR2 and neuropilin-1, suggesting that dendritic cells in the CNS are capable of signaling through VEGF receptors." (PMID 30211113, 2018). "NRP1- and NRP2-targeted knockdown using shRNA infection in these cells significantly decreased PDGFRα and PDGFRβ tyrosine phosphorylation without affecting total PDGFR levels." (PMID 26410366, 2015). "We also found that, compared with cont-miR, the expression of NRP1 was significantly down-regulated in the AGS and MKN45 cell lines after infection with LV-hsa-mir-338." (PMID 24736504, 2014). "The contact of HTLV-1-infected DC with CD4+ T cells upregulates NRP-1 and HSPG within an hour followed by transmission of HTLV-1 to T cells and productive infection." (PMID 21114861, 2010). "The properties displayed by both GLUT1 and NRP-1, i.e. binding to the HTLV-1 SU and modulation of infection, are consistent with those expected for a receptor but many questions on their exact function remain unsolved." (PMID 21114861, 2010). "In addition to angiotensin-converting enzyme 2 (ACE2) and neuropilin-1 (NRP1), AXL acts as a spike protein receptor and mediates infection, especially in respiratory cells with low ACE2 expression." (PMID 40649848, 2025). "Such infection appears to be poorly correlated with levels of ACE2, TMPRSS2, or NRP1 expression." (PMID 40674406, 2025). "Expression of both NRP-1 and ACE2 in the olfactory tubercles may enhance SARS-CoV-2 entry, whereby the infection could further migrate centrally to reach the parolfactory gyrus and potentiate neurologic complications." (PMID 40584180, 2025). "Finally, using HEK293T cells, we found that inhibition of infection by Nrp1 was abolished by the deletion of its extracellular domain, suggesting that the extended ectodomain of Nrp1 on HTLV-1 virions inhibits infection." (PMID 37375521, 2023). "Furthermore, OM-ALI cells expressed genes for all the characteristic proteins that are important for viral entry and infection, such as TMPRSS-2, CTSB, CTSL, NRP-1, BSG, and furin." (PMID 38098019, 2023). "If other viral protein(s) are found to mediate entry, the cognate receptor, likely EphA2, NRP1, or integrins, can be identified, though it is possible that an as yet unidentified EBV receptor may also contribute to infection." (PMID 36630458, 2023). "Subsequent analysis of luciferase activity from the cultures revealed a significant decrease in infection in cultures with ectopic expression of full-length Nrp1, while cultures with the deletion mutant showed no change in infection." (PMID 37375521, 2023). "In spleen, blood and brain of naïve mice, Nrp-1 expression on the surface of CD8+ T cells was almost absent (< 2% 0 days post infection)." (PMID 38019895, 2023). "Evidence shows that interaction with NRP1 allows low levels of infection at high virus titers in the absence of ACE2 and promotes virus internalization." (PMID 37350967, 2023). "Neuropilin-1 (NRP1) has recently been found to enhance SARS-CoV-2 infectivity through the early pathway entry but is not necessary for infection." (PMID 35679253, 2022).
infection (continued). "Moreover, NRP1 serves as the receptor of SARS-CoV-2 with higher expression in cerebral cortex, which probably contributes to the brain injuries post infection." (PMID 35377064, 2022). "No reduction in viral load at 24 hpi was observed, demonstrating that NRP1 is not essential for infection." (PMID 36175400, 2022). "Infection of pancreatic β cells with SARS-CoV-2 attenuates pancreatic insulin levels and secretion and induces β cell apoptosis, which was partially reduced by NRP1 inhibition." (PMID 35955539, 2022). "NRP1, used as a control, did not promote infection but it significantly increased viral entry when co-expressed with ACE2 or ACE2 and TMPRSS2, recapitulating previous observations." (PMID 35931765, 2022). "Since SARS-CoV-2 infection in hamsters mimics human infection, therefore it was essential to understand the similarities between human (hu) and hamster (ha) receptors, especially ACE2 and NRP-1, and study their interactions with SARS-CoV-2 at the molecular level." (PMID 35014610, 2022). "Lastly, we observed that infection with H1N1 resulted in prolonged upregulation of the SARS-CoV-2 entry-related genes FURIN and NRP1 that was not linked to viral titres." (PMID 35840680, 2022). "Later, other receptors and entry cofactors of SARS‐CoV‐2 were uncovered, including AXL, NRP1, SCARB1 etc.,27, 28, 29 which may explain its infection in tissues with low ACE2 expression." (PMID 35917402, 2022). "In Vero E6 cells, hypoxia reduces the protein levels of ACE2 and neuropilin-1 (NRP1), which might in part explain the observed reduction of the infection rate." (PMID 34013835, 2021). "ACE2 mRNA expression increased from days 3 and 4 post infection, but the Neuropilin-1 mRNA expression did not vary over time." (PMID 34608167, 2021). "Angiotensin-converting enzyme 2 (ACE2) is the receptor for the spike protein and is responsible for the initiation of infection, although other host factors, such as TMPRSS-2 and neuropilin-1, may facilitate the viral entry process." (PMID 34634931, 2021). "The binding of the S1 CendR motif generated by the furin cleavage of Spike protein to NRP1 did not affect cell surface attachment but promoted cell entry and infection by SARS-CoV-2." (PMID 34961486, 2021). "Transfection efficiency > 80% at 20 multiplicity of infection (MOI) and the state of good cell growth suggested successful and stable lentivirus transfection, indicating that NRP1 sh1 RNA group may be used for subsequent experiments." (PMID 32472711, 2020). "In addition to ACE2 and TMPRSS2, other potential SARS-CoV-2 receptors, proteases and cofactors for infection have been suggested, including BSG (CD147) and neuropilin-1 (NRP1)." (PMID 33380340, 2020). "Infection of these cell lines by the WT, but not the mutant, virus increased in the presence of NRP1, providing further evidence that NRP1 requires a furin-cleaved substrate for its effects." (PMID 33082293, 2020). "Rv1997 or cation transporting P-type ATPase F (ctpF) is one such gene, which in addition to the regular cues of dormancy, is also upregulated in early infection, non-replicating persistence-1 (NRP-1) and NRP-2 states." (PMID 33042857, 2020). "Previous report showed that infection of myeloid DC by cell-free HTLV-1 particles is independent of NRP-1/BDCA4, viral binding being ensured by the DC-SIGN lectin." (PMID 30818370, 2019). "Our data show that, regardless of virus strain, the absence of Nrp1 on CD8 T cells at the time of infection resulted in a bias toward KLRG-1− CD127+ memory precursor phenotype cells at the expense of KLRG-1+ CD127− effector cells at the peak of the response." (PMID 31118303, 2019). "Although we cannot rule it out, we consider it unlikely the protocol we used to delete Nrp1 in memory CD8 T cells, terminating 2 days prior to transfer, affected the differentiation state of the CD8 T cells in a manner similar to deletion prior to infection." (PMID 31118303, 2019).